IL6 (interleukin 6)
Diseases named in the same sentence as IL6 in open-access papers (continued):
Sharing a sentence is not in itself a finding about the gene and the disease.
cancer (continued). "Interestingly, BMDC exposed to synchronized ferroptotic cancer cells (early, intermediate, late) in contrast to UVB-treated apoptotic cells did not produce substantial amounts of cytokines related to inflammation (IL-6, IL-12, TNF, IFN-β) and adaptive immune response (IL-10, IFN-γ)." (PMID 35760796, 2022). "Salivary levels of Interleukin-1α (IL-1 α), IL-6, IL-8, Vascular-Endothelial Growth Factor- α (VEGF- α) and Tumor Necrosis Factor- α (TNF- α) can support analysis of the progression of premalignant lesions of the tongue and could be used for cancer screening and early diagnosis." (PMID 36412636, 2022). "Finally, addition of CXB during pre-treatment of COX-2WT 4T1 cells with 5-FU reduced the levels of IL-6 and IL-1α detected in the peritoneum, further exposing the major contribution of COX-2 enzymatic activity for the inflammatory properties of CTX-treated cancer cells in vivo." (PMID 35440553, 2022). "Therefore, there has been an increased interest in the use of IL-6 inhibitors, such as tocilizumab or sarilumab, to treat irAEs, with the expectation that they will be efficacious in the treatment of irAEs, without any deleterious effects on cancer outcomes." (PMID 36081549, 2022). "It has been reported that inhibition of the MAPK pathway activates the JAK2/STAT3 pathway, and autocrine Interleukin 6 (IL-6) secretion and subsequent JAK2/ STAT3 activation may represent an unexpected route to overcome targeted inhibition of the MAPK pathway in BRAF mutant cancers." (PMID 36430869, 2022). "Hence, the suppression of the IL-6/STAT3 signalling pathway by cryptolepine, as well as inflammation, suggest that cryptolepine could be exploited as a cheaper and novel anti-cancer agent in the management of HCC and other cancers." (PMID 34078370, 2021). "Macrophages can produce proinflammatory mediators such as IL-6, TNF, IFN-γ, growth factors, including epidermal growth factor (EGF) and Wnt, proteases, ROS, and nitrogen substances that may produce a mutagenic microenvironment, further facilitating cancer initiation." (PMID 34965886, 2021). "Interestingly, IL-6 was also found to induce the production of Survivin, an inhibitor of apoptosis, in cancer cells; the authors also identified that mTOR/4E-BP1 signaling is activated in cancer cells as a response to CAF-secreted factors and plays a role in imparting chemoresistance." (PMID 34646829, 2021). "Notably, IL-6 was the most predominantly increased inflammatory molecule that has been found to be involved in tumorigenesis and cancer stemness and predominantly expressed in PGCCs rather than in diploid cancer cells." (PMID 34588424, 2021). "Indeed, treatment of normal RMF-EG fibroblasts with IL-6 and TNF-α, two abundant cytokines in the conditioned medium of MDA-MB-231 cancer cells, increased KDM2A protein level in a dose-dependent manner suggesting these two cytokines may play a role in stimulating KDM2A expression in fibroblasts." (PMID 33024266, 2021). "The characterisation of IL6-dependent signalling has suggested that specific targeting of its trans-signalling route might be a good strategy to block this cytokine’s pro-cancer effects without altering other important roles in homeostasis that normally rely on classic signalling." (PMID 34834425, 2021). "However, when it does not, uncontrolled, excessive, or persistent IL-6 production plays an essential role in the development of various pathologies such as inflammatory diseases and cancers, indicating that IL-6, although necessary, can also be dangerous for the patient." (PMID 34356982, 2021). "However, anti-IL-6 therapies have mainly demonstrated no benefit in several types of cancer." (PMID 34445170, 2021). "Thus, IL-6 has a negative impact on the activity of cancer cells." (PMID 33351844, 2020). "Hence, IL-6 is not cancer specific for a single type of cancer." (PMID 30038723, 2018).
cancer (continued). "However, the anti-cancer effects of icariin in MM cells had not been extensively investigated, although icaritin a hydrolitic product of icariin has been reported to modulate IL-6/JAK2/STAT3 signaling cascade in MM." (PMID 29899697, 2018). "Additionally, mRNA of interleukin 6 (Il6) was significantly altered in 3D mono-culture (with an approximately 10-fold decrease compared with the expression of Il6 in 2D cultured EMT6/GFP cells) and after co-culture with fibroblast (significant decrease comparing with 3D mono-cultured cancer cells)." (PMID 29435153, 2018). "However, CXCL1 secretion appeared to be cancer specific, whereas IL-6 did not." (PMID 29360827, 2018). "Considering IL-6-174G>C could affect the expression of IL-6 protein, independent of cancer type, clinical status of patients included in our meta-analysis could not be uniformed, therefore, we think this might be the reason of negative pooled association using the three genetic models." (PMID 28548958, 2017). "Therefore, Oligo-Fucoidan supplementation promotes cancer cell death and inhibits the ATM signaling activity, an effect that may be attributable to inhibition of IL-6 activity." (PMID 28928376, 2017). "Furthermore, tea inhibits the release of antiinflammatory cytokines such as interleukins (IL-6, IL-8, IL-10, IL-12), as well as the receptor activator of nuclear factor kappa-B ligand (RANKL), and acts as an anticancer agent by stimulating apoptotic processes in cancer cells." (PMID 26834707, 2015). "However, we suspect that this phenomenon does not result from IL-6 generation by cancer cells." (PMID 26486258, 2015). "Additionally, the IL-6- and/or MYC-driven mouse models of human BL and MM used in this study may lend themselves to the biological validation of CDKN1A and FANCD2 as molecular targets for new approaches to cancer therapy and prevention." (PMID 25838973, 2015). "IL-6 transmits major survival signals through various pathways, including PI3K/AKT, Ras/Raf/MEK-ERK1/2, JAK/STAT3, SHP2/RAFTK, and Src-family tyrosine kinase pathways, and each of these pathways may give the cancer cell alternative surviving reliance other than original intrinsic mutation." (PMID 25937967, 2014). "Immunohistochemical analysis showed that IL-6 was strongly expressed in macrophages in tissues surrounding tumors in cachectic mice, and IL-6 production of macrophage was significantly inhibited by the treatment with hochuekkito, although level of IL-6 in cancer cells was not altered." (PMID 23326296, 2012). "However, the regulation of IL-6 autocrine production in cancer cells is not fully understood." (PMID 21122157, 2010). "Despite IL-6 involvement in cancer cell resistance was well established for various types of cancers, this cytokine did not set itself up as the main actor of radio-and chemoresistance of Daudi and Namalwa cells, since they were weakly sensitive to anti-IL-6 antibodies." (PMID 19956602, 2009). "On the other hand, we did not observe any correlation between IL6 and CTCF expression levels in patients who underwent cancer recurrence (Figure A1(C))." (PMID 40143084, 2025). "In this setting, persistent IL-6 signaling leads to continual activation of STAT3, which not only supports cancer cell proliferation and survival but also reconditions the immune microenvironment." (PMID 40109347, 2025). "In cancer patients treated with ICIs, low rather than high post-ICI IL-6 levels, female sex and dual ICI therapy are independent risk factors for irAEs." (PMID 41019062, 2025). "The finding showed that increased secretion of IL-6 among both noncancerous cells (MCF-10A or HDF-n) and cancer cells (MDA-MB-231) after co-culture contributes to cancer cell invasiveness, and this was confirmed by an IL-6 inhibitor assay." (PMID 39400856, 2025).
cancer (continued). "EGCG decreased IL6 expression in monolayer cells but not in spheroids.While EGCG’s downregulation of IL6 and TNF in inflammationmodels and cancer cells is documented, its impact in spheroids is a novel exploration." (PMID 40821580, 2025). "Since IL6 has been shown to promote EMT and stem potential in both normal and cancer cells, we added its inhibitor in the medium before stimulating the cancer cells." (PMID 39349458, 2024). "It is important to consider that there are other activators of JAK/STAT3 pathway besides IL-6, and only individual nodes of the target, including IL-6 and IL-6R, are targeted by FDA approved agents, not necessarily in the context of cancer." (PMID 38313431, 2023). "In patients not diagnosed with cancer, 15% had elevated CRP, 33% had elevated IL‐6 and 25% had elevated YKL‐40." (PMID 36440611, 2023). "In patients diagnosed with cancer, age was less correlated with the biomarkers (IL‐6 r = 0.31; YKL‐40 r = 0.24) than it was in patients not diagnosed with cancer (IL‐6 r = 0.36; YKL‐40 r = 0.42)." (PMID 36440611, 2023). "Peripheral blood mononuclear cells supernatant also showed increased levels of IL-6, IL-8, IL-10, IL-18, macrophage inflammatory protein 1 gamma (MIP-1γ) (cancer-promoting) and TNF-α (cancer-suppressive)." (PMID 37681925, 2023). "CRP, IL‐6 and YKL‐40 were elevated in 44%, 60% and 45% of the cancer patients, and in 15%, 33% and 25% of the patients without cancer." (PMID 36440611, 2023). "Patients referred to the diagnostic unit, with a cancer diagnosis, with only elevated IL‐6, CEA, CA 19‐9 or CA‐125 had significantly shorter OS than patients with a cancer diagnosis, without elevated biomarkers." (PMID 36440611, 2023). "Detailed analysis using ELISA Kits showed increased secretion of IL-6 and MCP-1 into the medium in all co-cultures compared to cancer cell monocultures with or without irradiation." (PMID 37371868, 2023). "The higher levels of plasma VEGF-A, TNF-α, CCL2, IL-6, and IFN-γ were depicted in the Untreated Cancer TIF1-γ-DM group than in the Non-cancer TIF1-γ-DM group." (PMID 36357631, 2023). "In this study, high levels of plasma VEGF-A, TNF-α, CCL2, IL-6, and IFN-γ in the Cancer TIF1-γ-DM group, particularly those not undergoing any anticancer treatment, were excellent in distinguishing cancer among the anti-TIF1-γ antibody-positive DM patients." (PMID 36357631, 2023). "Cells in all co-cultures secreted increased the amount of IFN-α2, IL-6 and MCP-1 into the medium compared to cancer cell monocultures with or without irradiation." (PMID 37371868, 2023). "In our study, we observed an increased amount of IL-6, MCP-1 and IFN-α2 secretion in all co-cultures compared to cancer cell monocultures with or without irradiation." (PMID 37371868, 2023). "In patients not diagnosed with cancer, CRP correlated with IL‐6 (r = 0.59) and YKL‐40 (r = 0.34), and IL‐6 with YKL‐40 (r = 0.54)." (PMID 36440611, 2023). "Patients diagnosed with cancer within 3 months had higher plasma CRP (p < 0.001), IL‐6 (p < 0.001), YKL‐40 (p < 0.001), CA 19‐9 (p < 0.001), CEA (p < 0.001), CA‐125 (p = 0.0075) and PSA (p < 0.001) than patients not diagnosed with cancer." (PMID 36440611, 2023). "Chronic IR is found in malignant tumors, but not in benign tumors, and is presumed to contribute to cancer cachexia due to chronic exposure to proinflammatory cytokines, tumor necrosis factor (TNF)-α, IL-6, and insulin growth factor-binding protein." (PMID 35752767, 2022). "Fibrocytes secrete only IL23 and IFNγ, which were suppressed upon co-culture, whereas cancer cells or fibrocytes secrete CCL5, IL-1ra, CD54, CXCL10, MIF, CXCL1, IL-6, and IL-8, which was not affected by co-culture." (PMID 36241617, 2022). "As such, tocilizumab, an anti-IL-6 agent, was recently investigated and shown to be effective for management of ICB toxicities across various organ systems in 86% of 91 cancer patients without disease progression." (PMID 35770005, 2022).
cancer (continued). "Even though this rate is directly involved in the cancer ODE, it is not as sensitive as adipocyte and IL6 related parameters mentioned before." (PMID 35294447, 2022). "These CAFs located away from cancer cells, lacked elevated α-SMA expression, and secreted IL-6 and other inflammatory mediators." (PMID 36185262, 2022). "In oncology, daily oral administration of ginseng or ginsenoside Rb1 in mice bearing colon C26 cancer cells results in reduced levels of TNF-α and IL-6 cytokines in serum, without modifications of tumor growth." (PMID 36139563, 2022). "At present, the biologics acting anti-IL-6 are efficient only for MAS, which occurs during immunotherapy in cancers, but not for MAS related to sJIA and AOSD." (PMID 35457086, 2022). "Polar extract of Pleurotus ostreatus effects on IL-6 and TNF-α production in treated MCF-7 cancer cells and with negative control." (PMID 35250951, 2022). "The expression level of IL6 was also significantly higher in TNBC compared with non-TNBC tissues, whereas IL4 level was not different between cancer types." (PMID 35960749, 2022). "The TERT–NF-κB p65 interaction increased a subset of NF-κB-dependent gene expressions such as IL-6 and TNF-α, which are critical for inflammation and cancer progression, suggesting a noncanonical role for TERT in cancer regulation." (PMID 35741087, 2022). "In addition, IL-6/JAK/STAT3 signaling could induce “pituitary tumor transforming gene 1” (PTTG1) overexpression with subsequent induction of epithelial-mesenchymal transition, increasing the cancer stem cell population in LNCaP androgen-dependent PC cell lines." (PMID 34830209, 2021). "Clinicaly, postoperative IL-6 and CRP are known to be useful markers of postoperative morbidity, including infection, in cancer and non-cancer patients." (PMID 34768810, 2021). "Unlike cancer cells, the co-treatment of macrophages with ME and high FRH (41 °C) induced a strong up-regulation of IL-1β and IL-6 mRNA expression." (PMID 34201348, 2021). "This suggests that IL-6 is released by MDA-MB-231 and MCR cancer cells and not by activated UniCAR T-cells, which is in line with our previous publication and other studies." (PMID 32370811, 2020). "Although both of these anti-cancer drugs counteract the production of detrimental cytokines, including IL-6, IL-8 and MCP-1, neither ET743 nor PM01183 has yet been evaluated as able to limit the progression of cancer cachexia." (PMID 32824440, 2020). "The monoclonal antibodies affected cytokine secretion, including MCP-1, IL-6, and TNF-a, but the effect on cancer cell viability or survival have not been investigated." (PMID 33238461, 2020). "Another study showed a significant association between cholinesterase activities including BChE with IL-6 and TNF-α but not with CRP in frail elderly patients without cancer." (PMID 32375339, 2020). "Surprisingly, the main cytokines, IL-6 and TNF-α, usually assayed in cancer models, presented no changes in our conditions." (PMID 32472095, 2020). "Siltuximab is a chimeric monoclonal antibody that also binds IL-6; however, no studies have been published on its use in the management of CRS in cancer patients to date." (PMID 33344513, 2020). "The downregulation of IL-6 in CAFs mediated by shRNA failed to promote chemotherapeutic resistance and did not increase the activation of STAT3 in the cancer cells co-cultured with CAFs." (PMID 30927911, 2019). "Our laboratory has also demonstrated that chronically elevated IL-6 can increase STAT3 activation and FIS-1 expression in myotubes and skeletal muscle independent of a cancer environment." (PMID 30918582, 2019). "In line with this, Malaponte found a positive correlation between IL-6 and MMP-9 plasma concentrations in both DVT and non-DVT cancer patients." (PMID 32117207, 2019). "CC patients showed higher value of IL-8 (55.6-fold) but not IL-6 (9.8-fold) and TNF-α (1.6-fold) when compared with the control and with weight-stable cancer group." (PMID 30513776, 2018).
cancer (continued). "The mechanisms by which IL-6 contributes to the pathogenesis of IBD and cancer are not fully understood." (PMID 30154846, 2018). "In this study, higher serum levels of IL-1β, IL-6, IL-8, and TNF-α were observed in cancer patients of the locally advanced group than those of the normal and resected groups." (PMID 30513776, 2018). "Consistent with international consensus for cachexia diagnosis, our results demonstrate systemic inflammation in cancer cachectic vs. non-cachectic patients, with increased circulating CRP, IL6, TNFα, IL8, and IL5 levels." (PMID 28288584, 2017). "Further studies are required to elucidate the true negative rate and the statistical power of this study to show significant differences in plasma IL-6, TNF-α and monocyte HLA-DR expression between patients with and without cancer." (PMID 28692671, 2017). "Inflammatory pathways can trigger epigenetic switches from nontransformed to metastatic cancer cells via signalling involving NF κB and STAT3 transcription factors, microRNAs (Lin28 and let-7), and IL-6 cytokines." (PMID 27608040, 2016). "Nonetheless, we did not investigate possible regulation of IL-6 on other signaling pathways, such as IGF and NFκB, which were also reported to be important in CSC growth in other cancers in this study." (PMID 26675547, 2016). "No major alterations were found between the levels of the pro-inflammatory TNF, IL6, CCL2 and CCL5 and of the anti-inflammatory CD163 in macrophages cultured in the presence of cancer cells, with or without radiation exposure." (PMID 27513864, 2016). "Numerous human cancer cell lines, including HT-29, do not constitutively express p-STAT3 in vitro, however, previous studies have demonstrated that IL-6 can stimulate STAT3 activation in HT-29 cells." (PMID 25789077, 2015). "Compared to control group, higher plasma levels of CRP, fibrinogen, IL-6, TNF-α, IL-1β, MMP-9, VEGF, TF antigen, and sP-selectin were observed in cancer patients with and without DVT (P<0.01)." (PMID 26192925, 2015). "Spontaneous production of cytokines, such as IL-6, TNF-α, Il-1β and VEGF were significantly higher in both groups of cancer patients with and without DVT than those from healthy controls (p<0.0001)." (PMID 26192925, 2015). "HAMLET also triggered IL-6, IL-8, and TNF-α secretion in healthy, differentiated cells but not in carcinoma cells." (PMID 23505537, 2013). "Due to the capacity of Hyper-IL6, a fusion protein between IL6 and IL6Rα, to activate gp130 receptors independently of the presence of the ligand-binding IL6Rα subunit, these observations suggest that cancer-initiating cells may not always express sufficient IL6Rα subunits to respond to IL6." (PMID 20478049, 2010). "In many cancer types, recent studies have demonstrated that the hypermethylation of SOCS-1 is not controlled by the JAK/STAT pathway, and IL-6 cannot perform a role in cancer defense; on the contrary, it is involved in cancer development." (PMID 19457231, 2009). "Inflammatory proteins, such as IL-6 or CRP, are reported to be higher in cancer patients compared to non-cancer patients." (PMID 16740157, 2006). "We therefore investigated whether procoagulant EV and IL-6, as expression of thromboinflammation during VTE, would differ between patients with acute VTE, with or without active cancer, and cancer patients without VTE." (PMID 39858477, 2025). "Our datasets suggest that in response to MIT‐mediated chemotherapy, cancer cells also become senescent, but they do not express a typical SASP, as the expression levels of a number of key SASP factors such as IL1α, IL6, CXCL8, and MMP1 remained largely unchanged." (PMID 40265973, 2025). "Notably, some inflammation-related pathways were up-regulated exclusively by both cancer plasmid models without TAA but not TAA alone, including IL2/STAT5 signaling, IL6/JAK/STAT3 signaling, and interferon alpha response." (PMID 39254423, 2024).